HES1 (hes family bHLH transcription factor 1)
Diseases named in the same sentence as HES1 in open-access papers (continued):
Sharing a sentence is not in itself a finding about the gene and the disease.
Cerebral ischemia (5 papers, 2012 to 2025). Restriction of arterial blood supply to the brain associated with insufficient oxygenation to support the metabolic requirements of the tissue. "The Notch1/Hes1 signaling pathway can also facilitate the growth and maturation of neural stem cells in the hippocampus of rats with cerebral ischemia, ultimately enhancing neurological function." (PMID 38891776, 2024). "The Notchl/Hes1 signaling pathway is capable of enhancing the proliferation and differentiation of hippocampal neural stem cells in rats with cerebral ischemia, leading to the improvement of neurological function." (PMID 38891776, 2024). "Here, we show that Notch signaling pathway is activated as evidenced by the up-regulation of Notch-1, NICD, RBP-JK and Hes-1 in activated microglia in experimentally induced cerebral ischemia and OGD induced activated BV-2 microglia." (PMID 28288585, 2017). "Real-time RT-PCR analysis for Hes1 gene in striatum after MCAO showed that in EA group, Hes1 mRNA rapidly increased to the maximum at 2 h after reperfusion (P < 0.05 vs. before I/R), and then gradually returned to the its pre-brain ischemia level." (PMID 22989188, 2012). "Further research is needed to determine whether and how vascular endothelial growth factor (VEGF), Notch, and Hes1 play roles in cerebral ischemia." (PMID 37309759, 2023).
Ewing sarcoma (5 papers, 2013 to 2025). A small round cell tumor that lacks morphologic, immunohistochemical, and electron microscopic evidence of neuroectodermal differentiation. "Another example of functionally inactive NOTCH1 with uncoupling HES1 expression was evidenced by cytoplasmic staining in Ewing's sarcoma." (PMID 40387567, 2025). "HES1 expression has been reported to be uncoupled from Notch signaling in Ewing’s sarcoma and stimulation of HES1 transcription by sonic hedgehog (Shh) pathway occurs in mesodermal and neural stem cells." (PMID 23816051, 2013).
fatty liver disease (5 papers, 2011 to 2025). A reversible condition wherein large vacuoles of triglyceride fat accumulate in liver cells via the process of steatosis. "Hes6 plays a complementary role in circadian regulation by antagonizing the expression of Hes1 and has been shown to attenuate hepatic steatosis." (PMID 41007411, 2025). "More specifically, the knock-down of hepatic GR in mouse models improved hepatic steatosis; GR may act partly by repressing the transcription of the hairy enhancer of the split 1 (Hes1) gene." (PMID 38459229, 2024). "However hepatic transcription of another Notch target, the transcription factor Hes1, which has been implicated in the regulation of hepatic lipid metabolism and fatty liver disease (FLD), was unchanged (data not shown)." (PMID 21698231, 2011).
ischemia (5 papers, 2015 to 2025). A hypoperfusion of the BLOOD through an organ or tissue caused by a PATHOLOGIC CONSTRICTION or obstruction of its BLOOD VESSELS, or an absence of BLOOD CIRCULATION. "The immunofluorescence of Notch-1, NICD, RBP-JK, Hes-1 in activated microglia around the peri-ischemia cortex in I/R rats and NS rats was noticeably enhanced." (PMID 28288585, 2017). "The protein expression of Notch-1, NICD, RBP-JK and Hes-1 in the brain tissue of MCAO rats was also augmented following ischemia and was also attenuated with scutellarin treatment at 1 and 3 days." (PMID 25600517, 2015). "Furthermore, the activation of NOTCH/HES1/AKT signaling contributes to cardioprotection against ischemia and reperfusion injury." (PMID 39010883, 2024). "Indeed, HS can suppress Notch signaling as manifested by the decreased protein expression of Notch-1, NICD, RBP-JK and Hes-1 in peri-ischemia area and OGD activated BV-2 cells." (PMID 28288585, 2017).
lung adenocarcinoma (5 papers, 2013 to 2025). A carcinoma that arises from the lung and is characterized by the presence of malignant glandular epithelial cells. "The protein levels of downstream targets are also elevated, and the overexpression of Hes1 has been previously reported in lung adenocarcinoma." (PMID 23671619, 2013). "In addition, STAT3 inhibitors currently being tested in clinical trials should be used with caution, at least in tumors in which the NOTCH4 pathway and thus HES1 play a protumorigenic role, as in lung adenocarcinoma." (PMID 37268635, 2023). "In lung adenocarcinoma, GALNT2 exerts oncogenic effects via the Hes1-PTEN-PI3K/AKT cascade to amplify malignant phenotypes." (PMID 40755759, 2025). "Focusing on the high-proportion subtype of lung adenocarcinoma (LUAD), research has found that Hes1 expression is significantly elevated in EGFR-TKI-resistant cells." (PMID 40755759, 2025). "In lung adenocarcinoma, GALNT2 was found to regulate the proliferation and mobility of cancer cells via activating the Notch/Hes1-PTEN-PI3K/Akt axis." (PMID 36110252, 2022).
lymph node metastasis (5 papers, 2019 to 2025). "HES1 was found to be associated with tobacco (88.9%; P = .04), tumor size (90.2%; P < .001), tumor vaginal involvement (89.2%; P < .001), lymph node metastasis (87.7%; P < .002), and FIGO stage (89.2%; P < .001)." (PMID 30615540, 2019). "There was a significant correlation of HES1 or Slug expression with tumor size (P=0.0262; P=0.0092), lymph node metastasis (P=0.0129; P=0.0060) and advanced TNM stage (P=0.0001; P=0.0005)." (PMID 33390847, 2021). "Another report claimed that highly expressed DLX6-AS1 was associated with lymph node metastasis and poor prognosis of OC patients, and downregulation of DLX6-AS1 blocked the expression of Notch1, p21, and Hes1, leading to the suppression of proliferation, migration and invasion in OC cells." (PMID 32774164, 2020). "In addition, CRC patients with lymph node metastasis had higher HES1 levels compared with those without lymph node metastasis." (PMID 37957183, 2023).
multiple myeloma (5 papers, 2013 to 2022). "Data from the real-time PCR assay showed that the mRNA expression levels of the Jag2 gene and its downstream gene Hes1 were both significantly down-regulated after the myeloma cells were treated with ATO while the expression of the tumor suppressor gene PTEN was up-regulated." (PMID 23497375, 2013). "In this study, the expression changes of PTCH1, GLI1, GLI2, Hes1, and SHH in the multiple myeloma drug-resistant cell line RPMI 8226/R were first detected." (PMID 35813864, 2022). "The results showed that the expression levels of PTCH1, GLI2, Hes1, and SHH in RPMI 8226/R were greatly increased compared with the multiple myeloma drug-sensitive cell line RPMI 8226/S, while the expression level of GLI1 was notably decreased." (PMID 35813864, 2022).
small cell lung carcinoma (5 papers, 2009 to 2025). Small cell lung cancer (SCLC) is a highly aggressive malignant neoplasm, accounting for 10-15% of lung cancer cases, characterized byrapid growth, and early metastasis. "Breakthroughs have also been made in the field of small cell lung cancer (SCLC) research, where Hes1 has been identified as a key mediator of chemotherapy resistance." (PMID 40755759, 2025). "Similarly, in small-cell lung cancer cells, VPA activated Notch signaling by an increase of Notch1, Notch target gene HES1, and p21 expression, which resulted in the inhibition of growth of cancer cells and cell cycle at G1 phase." (PMID 34068438, 2021). "High expression of E2F-1 also has been shown in small cell lung cancer, and these tumors do not express Hes-1." (PMID 19891787, 2009).
T-cell acute lymphoblastic leukemia (5 papers, 2010 to 2025). Acute lymphoblastic leukemia of T-cell origin. "Additionally, Hes1 directly inhibits the expression of the BBC3 gene (encoding the pro-apoptotic factor PUMA) in T-cell acute lymphoblastic leukemia (T-ALL), thereby suppressing oncogenic stress-induced apoptosis during T-cell transformation." (PMID 40755759, 2025). "In vivo studies have confirmed that the IDH1-R132H mutation upregulates Hes1 expression and downregulates PTEN expression by activating the Notch1 pathway, thereby activating the PI3K/AKT pathway and promoting malignant behavior in T-cell acute lymphoblastic leukemia (T-ALL) cells." (PMID 40755759, 2025). "Interestingly, HES1, associated with Notch activation, was essential to inhibit the progression of B-cell acute lymphoblastic leukemia rather than T-cell acute lymphoblastic leukemia." (PMID 36389757, 2022).
T-cell leukemia (5 papers, 2009 to 2018). A malignant disease of the T-lymphocytes in the bone marrow, thymus, and/or blood. "In T cell leukemia, Notch signaling through one of its target gene, Hes1, sustains NF-κB activation by repressing expression of deubiquitinase CYLD." (PMID 29889863, 2018). "Recently, a study suggested that the activation of the Notch1 signaling pathway may contribute to adult T-cell leukemia and that Hes1 is upregulated in leukemic samples." (PMID 27681508, 2016). "Conversely, CYLD expression in T-cell leukemia was regulated by transcriptional repression by Hes1." (PMID 24495516, 2014).
triple-negative breast carcinoma (5 papers, 2019 to 2022). An invasive breast carcinoma which is negative for expression of estrogen receptor (ER), progesterone receptor (PR), and human epidermal growth factor receptor 2 (HER2). "We selected MDA-MB-231 and HCC-1937 because these cell lines derived from triple-negative breast cancer and expressed endogenous high level of HES1 protein as well as Slug." (PMID 33390847, 2021). "Similarly, the miR-17-92 promoter has binding sites for HES1, a transcriptional repressor in the Notch signaling pathway which is overexpressed in triple-negative breast cancer." (PMID 31581940, 2019). "Celastrol can reduce the activation of Notch-1 and the expression of HES-1 and HEY-1 of the downstream target protein and inhibit the stem cells of triple-negative breast cancer, thereby reducing the possibility of distant metastasis." (PMID 36506508, 2022).
acute myeloid leukemia (4 papers, 2018 to 2025). Acute myeloid leukemia (AML) is a group of neoplasms arising from precursor cells committed to the myeloid cell-line differentiation. "Although a role for Notch in regulation of Flt3 in homeostatic lymphopoiesis has yet to be established, canonical Notch target Hes1 transcriptionally represses Flt3 expression in Acute Myeloid Leukemia (AML)." (PMID 34394130, 2021). "HES1 downregulation induces growth arrest and apoptosis in acute myeloid leukemia (AML) cells; thus, HES1 may be a novel target for the treatment of AML." (PMID 29665790, 2018). "Under normal circumstances, Hes1 is lowly expressed in acute myeloid leukemia (AML), and the Notch pathway exists in AML but is not activated." (PMID 40755759, 2025).
Anxiety (4 papers, 2019 to 2025). Intense feelings of nervousness, tension, or panic often arise in response to interpersonal stresses. "This study investigates the role of HMGB1 in anxiety and depression-like behaviors associated with the microglial Notch1/Hes-1 pathway in CRS mice." (PMID 39789446, 2025). "siRNA knockdown of HMGB1 in microglia significantly reduced Notch1/Hes-1 pathway proteins and inflammatory factors, highlighting HMGB1’s role in activating the Notch1/Hes-1 pathway and contributing to anxiety-depressive-like behaviors in CRS mice." (PMID 39789446, 2025). "Drawing on prior research, our investigation will focus on the effects of HMGB1 and the Notch1/Hes-1 pathway on anxiety and depression symptoms in CRS, as well as their mechanisms within hippocampal microglia." (PMID 39789446, 2025). "In this study, compared to the control group, CRS mice with anxiety and depression showed significantly increased expression levels of Notch1/Hes-1, TNF-α, IL-1β, and IL-6 in the hippocampal region." (PMID 39789446, 2025). "HMGB1 appears to trigger neuroinflammation by activating the Notch1/Hes-1 pathway in hippocampal microglia, contributing to the emergence of anxiety and depression-like symptoms." (PMID 39789446, 2025). "This study found that CRS mice with severe anxiety-depressive symptoms had significantly increased hippocampal expression levels of Notch1/Hes-1, indicating the importance of microglial Notch1/Hes-1 pathway activation." (PMID 39789446, 2025). "Behavioral analyses suggested that Math2-Cre;Hes1 cKO mice had increased fear retention and anxiety levels." (PMID 31160641, 2019). "Inactivation of Hes1 in excitatory neurons of adult mice led to abnormal fear and anxiety behaviors concomitantly with higher neuronal excitability in the amygdala." (PMID 31160641, 2019). "Interestingly, Hes1 was also induced in the early (0–1 h) time window upon acute exercise in skeletal muscle tissue, and another study showed that the inactivation of Hes1 in excitatory neurons resulted in abnormal fear and anxiety behaviors." (PMID 38217668, 2024). "Thus, inactivation of Hes1 in excitatory neurons led to abnormal fear and anxiety, suggesting that Hes1 plays an important role in the function of post-mitotic excitatory neurons in the adult brain." (PMID 31160641, 2019). "Furthermore, inactivation of Hes1 in excitatory neurons resulted in abnormal fear and anxiety behaviors concomitantly with higher neuronal excitability in the amygdala, while inactivation of Hes1 in inhibitory neurons resulted in increased sociability and perseverative tendencies." (PMID 31160641, 2019). "This study confirms that CRS mice exhibit symptoms of anxiety and depression, with elevated HMGB1 expression and stimulation of the Notch1/Hes-1 pathway in hippocampal microglia." (PMID 39789446, 2025). "HMGB1 activates the microglial Notch1/Hes-1 pathway in CRS mice, promoting neuroinflammation and anxiety and depression-like behaviors." (PMID 39789446, 2025). "Thus, the effect of Hes1 on anxiety is relatively mild, if any, and increased anxiety might not be caused directly by Hes1 inactivation but rather may be secondary to strongly retained fear memory." (PMID 31160641, 2019). "While the total traveled distance was not significantly different between Math2-Cre;Hes1 cKO and wild-type control mice, the cKO mice spent a significantly shorter time in the center area than did the wild-type control mice, suggesting that they had a mild increase in anxiety levels." (PMID 31160641, 2019).
bladder cancer (4 papers, 2017 to 2023). "Transcription factor motif analysis revealed HES1 to be enriched at KDM6A peaks identified in the T24 bladder cancer cell line; moreover, it has a truncating mutation in KDM6A and lacks a demethylase domain." (PMID 36980177, 2023). "Therefore, we plotted the correlation between HHEX, HES1 expression, and the expression of genes associated with the term ‘regulation of developmental process’ in the normal-immortal cluster for primary bladder cancer." (PMID 36980177, 2023). "This strategy identified a large module of Luminal TFs, including known Luminal-associated TFs (e.g., FOXA1/GATA3/PPARG), as well as TFs with yet unexplored roles in Luminal bladder cancer biology (e.g., HES1, FOXQ1, ZBTB7C, MECOM, GRHL2/3, and TBX3)." (PMID 36944729, 2023). "The low-expression level of HES1 is associated with EMT and metastatic properties in bladder cancer." (PMID 36430344, 2022). "In contrast, downregulation of HES1 in bladder cancer enhanced vimentin and reduced E-cadherin levels, which triggers an EMT phenotype and malignant progression." (PMID 28122586, 2017).
Cognitive impairment (4 papers, 2013 to 2026). Abnormal cognition is characterized by deficits in thinking, reasoning, or remembering. "AGEs promote the astrocytic differentiation of cultured neurospheres by inhibiting neurogenesis through the Notch-Hes1 pathway, providing a potential therapeutic target for hyperglycemia-related cognitive deficits." (PMID 24366068, 2013). "That is, AGEs promote the astrocytic differentiation of cultured neurospheres by inhibiting neurogenesis the through Notch-Hes1 pathway, providing a potential therapeutic target for hyperglycemia-related cognitive deficits." (PMID 24366068, 2013). "In APP/PS1 transgenic mice, upregulation of Notch1 and Hes1 alleviates cognitive impairment." (PMID 41596253, 2026). "Altogether, these findings reveal that modulating the HO-1/MAPK, P13K/Akt, SIRT1- NLRP3, and Notch/HES-1-NF-κB signaling pathways might be the mechanism of AG in mitigating neuroinflammation, cognitive impairment, depression, and AD." (PMID 37920216, 2023). "In summary, our results identified that agomelatine could improve cognitive impairment and ameliorate AD-like pathology in APP/PS1 mice via activating DHCR24 signaling and inhibiting Akt/mTOR and Hes1/Notch1 signaling pathway." (PMID 35153715, 2021).
diabetes (4 papers, 2021 to 2023). "Polydatin reduced MI/R cardiac damage during diabetes by activating the Notch1/Hes1-dependent Pten/Akt signaling pathway." (PMID 36235012, 2022). "Furthermore, several genes involved in the endocrine specification and diabetes development were significantly downregulated, such as HES1, INSM1, HNF1A, NEUROD1, NGN3, NKX2.2, GIPR, MNX1, PROX1, TCF7L2, and HHEX." (PMID 33473118, 2021). "In addition, genes in the mature onset diabetes in young people (hsa04950) pathway (such as HES1, GCK, FOXA3, MAFA, HNF4A, HHEX, and PDX1) were increased in stages II to IV; these genes are related to insulin secretion and the maturation of pancreatic β-cells." (PMID 33897780, 2021). "In the “Maturity onset diabetes of the young” pathway, the upregulation of HHEX and downregulation of HES1 could increase the expression of NEUROG3 and outcomes such as the Insulin signaling pathway." (PMID 36835058, 2023).
injury (4 papers, 2016 to 2024). Damage inflicted on the body as the direct or indirect result of an external force, with or without disruption of structural continuity. "Research has also shown that PHC can alleviate apoptosis and endoplasmic reticulum stress and trigger the Hes1/Notch1 pathway, effectively mitigating the effects of lipopolysaccharide-induced acute lung injury." (PMID 38671448, 2024). "In vivo experiments showed that blocking the Notch signaling pathway in mice reduced Hes1 levels and increased susceptibility to APAP-induced liver injury." (PMID 36901771, 2023). "A well studied downstream target of Notch that has been shown to inhibit neurogenesis is the transcription factor hairy and enhancer of split 1 (Hes1) and it is known that traumatic brain injury induces Hes1 downregulation as a way to increase neurogenesis and adapt to damage." (PMID 27195011, 2016). "In this study, we found that the expression of Notch, Hes1 and Hss5 increased after acute craniocerebral trauma, and was positively correlated with injury severity, which indicated that Notch signaling could be used as a reliable indicator to assess acute brain injury." (PMID 29447233, 2018).
metastatic tumors (4 papers, 2012 to 2024). "This shows that the downstream Notch pathway mediator Hes1 is essential for the development of omental metastatic tumors." (PMID 38575576, 2024). "HES1 expression and consequently the number of stem cells and tumor progression can be reduced by inhibiting the expression of ligand DI1-4 in metastatic tumors." (PMID 31198409, 2019). "However, Hes1 and MMP14 expression levels were unrelated to survival for patients with metastatic diseases." (PMID 26650241, 2015). "Furthermore, significantly higher nuclear expression of Notch1, -3 and -4, HES-1, and HEY-1 (all p≤0.001) was noted in locally advanced and metastatic tumours compared to resectable cancers." (PMID 23226563, 2012).